CEP76 (centrosomal protein 76)
Description:
Centrosomal protein involved in regulation of centriole duplication. Required to limit centriole duplication to once per cell cycle by preventing centriole reduplication.
Synonyms: C18orf9; HsT1705; FLJ12542
Tractability: PROTAC: ubiquitination databases record sites on it.
Gene: Protein-coding gene on chromosome 18 (12,661,833 to 12,702,777, reverse strand). Ensembl gene ENSG00000101624.
Subcellular location: Cytoplasm, cytoskeleton, microtubule organizing center, centrosome; Cytoplasm, cytoskeleton, microtubule organizing center, centrosome, centriole
Subcellular location (Human Protein Atlas): Flagellar centriole; Microtubules; Mitotic spindle; Perinuclear theca; Primary cilium; Cytosol; Nucleoplasm; Plasma membrane
Pathways (Reactome):
Cell Cycle: AURKA Activation by TPX2; Loss of Nlp from mitotic centrosomes; Loss of proteins required for interphase microtubule organization from the centrosome; Recruitment of NuMA to mitotic centrosomes; Recruitment of mitotic centrosome proteins and complexes; Regulation of PLK1 Activity at G2/M Transition
Organelle biogenesis and maintenance: Anchoring of the basal body to the plasma membrane
Gene Ontology:
Molecular function: protein binding
Biological process: regulation of centriole replication
Cellular component: centriole; centrosome; protein-containing complex; cytosol
Genetic constraint (gnomAD): Loss-of-function variants: 27 observed, 52.01 expected, observed/expected ratio (o/e) 0.52, 90% interval 0.38 to 0.72. The upper end of that interval is the gene's LOEUF score, 0.72, which puts it in group 2 of 6, group 1 being the genes least tolerant of losing a copy. Missense variants: 567 observed, 685.73 expected, observed/expected ratio (o/e) 0.83, 90% interval 0.77 to 0.89. Synonymous variants: 225 observed, 240.38 expected, observed/expected ratio (o/e) 0.94, 90% interval 0.84 to 1.04.
Homologues: Orthologues: chimpanzee CEP76 (99% identical), macaque CEP76 (99% identical), rabbit CEP76 (98% identical), dog CEP76 (98% identical), mouse Cep76 (98% identical), rat Cep76 (97% identical), pig CEP76 (97% identical), guinea pig CEP76 (92% identical), tropical clawed frog cep76 (81% identical), zebrafish cep76 (69% identical), Drosophila melanogaster Cc2d2a (19% identical), Caenorhabditis elegans mks-6 (11% identical). Paralogues in human: CC2D2A (25% identical), CC2D2B (22% identical).
Diseases named in the same sentence as CEP76 in open-access papers:
CEP76 is named in the same sentence as 8 diseases in open-access papers, as found by Europe PMC text mining. Sharing a sentence is not in itself a finding about the gene and the disease. The quoted sentences say what the papers report.
Beckwith-Wiedemann syndrome (1 paper, 2016). Beckwith-Wiedemann syndrome (BWS) is a genetic disorder characterized by overgrowth, tumor predisposition and congenital malformations. "TSSC4 is associated with Beckwith Wiedemann syndrome which is incidentally also characterized by microcephaly in addition to other physical manifestations and interacts with CEP76, a candidate gene associated with autosomal recessive congenital microcephaly and found in ciliated cells." (PMID 29333229, 2016).
breast tumors (1 paper, 2010). "We have also pointed to other 18p TSG candidates including ZFP161, CEP76, PPP4R1 and PTPN2 whose involvement might explain the aggressive phenotype of breast tumors with 18p loss." (PMID 20698951, 2010).
male infertility (1 paper, 2024). The inability of the male to effect fertilization of an ovum after a specified period of unprotected intercourse. "In the absence of CEP76, essential components of the sperm tail are unable to enter the ciliary lobe, meaning less or minimal incorporation into the growing tail and thus male infertility." (PMID 38570187, 2024).
Meckel syndrome (1 paper, 2023). "Closely related to CEP76 and DRC7 are two inactive proteins C2D2A and C2D2B, the former being a part of the tectonic-like complex and is associated with Meckel syndrome." (PMID 37164157, 2023).
sarcoma (1 paper, 2024). A usually aggressive malignant neoplasm of the soft tissue or bone. "Our data revealed a second function of CEP76 in male germ cells—a role in suppressing supernumerary centrioles, analogous to its role identified in human sarcoma cells in vitro." (PMID 38570187, 2024).
cancer (4 papers, 2010 to 2022). A tumor composed of atypical neoplastic, often pleomorphic cells that invade other tissues. "This list of commonly mutated cancer genes contained 3 centrosome genes: CEP76, CTNNB1, and NPM1, which were included in our analysis." (PMID 32681070, 2020). "Depletion of CEP76 drives the accumulation of centrosome intermediates in certain types of cancer cells." (PMID 20698951, 2010). "Taking all these data into account, we identified the following candidates as potential causes of CA in human cancer: gain of function of CEP19, CEP72, CTNNB1, PTK2, NDRG1, SPATC1, TBCCD1; and loss of function of CEP76, MCPH1, NEURL4, NPM1." (PMID 32681070, 2020). "Centrosomal protein 76 kDa (CEP76) appears to suppress centriole amplification, suggesting that elevated miR3653 may contribute to the dormancy of liver CSCs via CEP76, as centriole numbers are strictly controlled, and an increase in their copy number is considered among the hallmarks of cancer." (PMID 36556285, 2022). "A panel of eight cancer driver genes (CCNE1, TPX2, ELF3, FANCL, JAK2, GSK3B, CEP76, and SYK) were differentially expressed in recurrent TNBCs, and were also overexpressed in TCGA and METABRIC." (PMID 30665374, 2019).
CEP76 also shares sentences with these, for which no sentence is quoted: congenital microcephaly (1 paper); microcephaly (1).